RB1 (RB transcriptional corepressor 1)
Diseases named in the same sentence as RB1 in open-access papers (continued):
Sharing a sentence is not in itself a finding about the gene and the disease.
tumor (continued). "RB1CC1 conferred a significant relative hazard (p<0.0001) in addition to the risks of chemotherapy, tumor size, lymph node status, TNM class, ER, PR, triple-negative cancer, and RB1." (PMID 21203526, 2010). "Statistical analysis of LOH in MLH1, CDKN2A and RB1 genes and clinicohistopathological features of the disease disclosed that LOH in MLH1 and CDKN2A correlates only with tumour grading." (PMID 15083191, 2004). "Alternatively, we reported here that targeting the downstream core cancer drivers (CDRs) of RB1/E2F1, either through gene silencing using specific CRISPR-Cas13 or with small molecular inhibitors, may achieve anti-tumor goals." (PMID 41492471, 2026). "We demonstrated the transition of PTC to SCC, in which tumor cells carried none of the common driver mutations (e.g. BRAF or RAS), but showed biallelic inactivation of KEAP1, STK11, and RB1." (PMID 40600748, 2025). "The mesenchymal cells demonstrated a decrease in expression of tumor suppressor and negative cell cycle regulator RB1 and tumor and metastasis suppressor KISS1 while OVCAR had an increase in expression of these two genes." (PMID 41028875, 2025). "Fluorescence in situ hybridization (FISH) analysis indicated a hemizygous deletion of the RB1 locus in 36% of tumor cells, with no MDM2 amplification detected." (PMID 41230282, 2025). "While INK4A canonically affects the RB1 cell cycle pathway, it also plays RB1-independent tumor suppressor roles, including negatively regulating accumulation of ROS and DNA damage." (PMID 40802750, 2025).
tumor (continued). "TSGs can be broadly categorized into several types, including ‘gatekeepers’ (e.g., RB1 and APC) that directly regulate cell growth, ‘caretakers’ (e.g., BRCA1 and ATM) that maintain genomic integrity, and ‘landscapers’ that modulate the tumor microenvironment [e.g., PTEN and TGFβ]." (PMID 40227591, 2025). "Regarding MCPyV-positive MCCs, pRB is targeted by the Large T antigen (LT) of MCPyV as research has shown that MCPyV-LT strongly binds to RB1 only, inactivating it and thus promoting MCC tumor growth in MCPyV-positive MCCs." (PMID 40227764, 2025). "In contrast, variants in STK11, PMS2, MUTYH, and RB1 were primarily classified as VUS and did not demonstrate an apparent relationship with tumor aggressiveness." (PMID 41595443, 2025). "In contrast, downregulation of NUDT15 was not specifically detected in RB1‐deleted samples because the CN was intact for tumor microenvironment cells." (PMID 40904703, 2025). "At the tumour core, PTEN and RB1 demonstrated exclusivity in 3 out of 9 patients for both genes." (PMID 38846976, 2024). "Both in Bueno and TCGA cohorts, we observed that several tumours with high CDKN2A transcripts did not display any defect or low expression of RB1." (PMID 36453028, 2024). "PICRUSt analyses outlined 65, 43 and 74 functions altered in fecal samples from mice with end point TRAMP-C2 tumours, Pten−/−; Rb1+/+ and Pten−/−; Rb1−/− tumours compared to their corresponding no tumour controls, respectively." (PMID 38654015, 2024). "We also noted 0.7 ± 0.2% and 0.5 ± 0.2% Ruminococcaceae_g_2 increase in both Pten−/−; Rb−/− and Pten−/−; Rb1+/+ fecal samples compared to no tumour controls." (PMID 38654015, 2024). "In conclusion, this work identifies a crucial function for RB1 in human retinal development and suggests that the deletion of RB1 alone is not sufficient for tumor development, at least in human retinal organoids." (PMID 38835365, 2024). "This elevated oxygen demand is further exacerbated by the uncontrolled proliferation of tumor cells lacking RB1." (PMID 38672640, 2024). "Each tumor genome was classified according to their HRD and RB1 status, resulting in six groups: BRCA1-HRD & RB1 altered (n = 13); BRCA1-HRD & RB1 wild-type (n = 36); BRCA2-HRD & RB1 altered (n = 8); BRCA2-HRD & RB1 wild-type (n = 20); HRP & RB1 altered (n = 4); or HRP & RB1 wild-type (n = 45)." (PMID 38837893, 2024). "We observed that the Shannon index of the microbiota of Pten−/−; Rb1−/− mice was reduced by 19 ± 8% compared to mice without tumours (p = 0.02, two-sided Welch’s t-test), but not for Pten−/−; Rb1+/+ tumour bearing mice." (PMID 38654015, 2024). "Moreover, it is of interest that RB transcriptional corepressor 1 (RB1), a well-known tumor-suppressor gene, is located on chromosome 13q14.2." (PMID 38256198, 2024). "Importantly, we observed that depletion of NDRG1 resulted in a proliferation advantage of BCa cells, comparable to the effect observed when perturbing expression of the well‐known tumour suppressor Rb1, indicating a role of NDRG1 as a tumour suppressor in BCa." (PMID 37854018, 2024). "The tumour cells established in this work represent a tumour with MYCN over-expression but without RB1 inactivation or other genetic lesions." (PMID 37606819, 2024).
tumor (continued). "DNMT3A and RB1 are deleted in the MPM700 cell line and tumor." (PMID 37345150, 2023). "Further, in approximately 2% of patients, RB develops without any RB1 alterations and is instead driven by oncogenic amplification of MYCN on chromosome 2, which is also associated with aggressive tumor behavior." (PMID 37239954, 2023). "Compared with Cluster1, Cluster2, with poorer prognosis, had chromosomal amplification of various tumor-promoting gene loci, such as E2F3, MYC, and GATA3, and partial or complete deletion of the chromosome where the tumor suppressor gene PTEN and RB1 loci are located." (PMID 37767092, 2023). "Somatic alterations in pre-specified genes (ATM, RB1, FANCC and ERCC2) or increased tumor mutational burden did not improve the positive predictive value of cCR." (PMID 37783966, 2023). "Among the five tumor samples with no phosphorylated CDK4 (profile A), we identified two samples with mutated RB1 (a nonsense and a frameshift mutation)." (PMID 37964967, 2023).
tumor (continued). "RB1 is a tumor suppressor that is not found in TNBC and is currently being studied to understand its effects within specific therapies." (PMID 38137912, 2023). "Notably, miR-221-3p has been reported to act as a tumor promoter in multiple types of cancers, involved in tumor invasion, metastasis, proliferation and chemotherapy resistance by regulating the expression of target genes such as VASH1, PARP1, RB1." (PMID 36991449, 2023). "The cell cycle alteration induced by IFN-β was not significant in non-transformed cell counterparts, nor in RB1+/+ tumor cells with an abundant presence of underphosphorylated RB1." (PMID 37182173, 2023). "It has also been noted that RB1 has additional cancer relevant non-canonical functions that likely contribute to its tumor suppressor activity, a topic to which we return below." (PMID 35368709, 2022). "Conversely, the forced expression of miR-17-5p and miR-19a is able to repress the expression of RB transcriptional corepressor 1 (RB1) and phosphatase and tensin homolog (PTEN), respectively, thus explaining their ability to enhance the proliferative capacity of tumor cells." (PMID 35804851, 2022). "Intriguingly, we identified copy number alterations (CNAs) of various oncogenes and tumor suppressors (e.g. Yap1, Braf, Foxo1, Akt3 and Rb1) in RMS tumors developing in DK mice, which might play important roles for tumor formation and growth." (PMID 36376321, 2022). "The RB1 and MYCNA mutations often co-occur, though tumours with MYCNA without RB1 loss-of-function have been described." (PMID 35729105, 2022). "Such enhanced utilization of OXPHOS results in greater mitochondrial activity and higher ATP generation in tumor cells lacking RB1 and HK1." (PMID 36291051, 2022). "The analysis confirmed a higher mutational burden in the Non-Resp group with more deleterious alterations in the PTEN, RB1, and NF1 genes, which are well-known tumor suppressor genes in GB, indicating a more aggressive phenotype in accordance with our previous results." (PMID 36132155, 2022). "For the benefit of patient, the tumor tissues were directly eliminated with LASER operations and not available for searching the second mutation in the RB1 gene." (PMID 36714839, 2022). "We next treated RB1 non-mutated tumor cells with 10 μM GSK503 for 72 h and found that the binding of EZH2 to the RB1 promoter was abolished, which led to a decrease in H3K27me3 in the RB1 promoter." (PMID 36175480, 2022). "Validated targets for miR‐106b‐5p with negative correlation at the mRNA level included the tumour suppressors RB1 and RBL245 (Pearson's r = −.32 and −.27; P = 3.4e − 26 and 5.9e − 17)." (PMID 35182081, 2022).
tumor (continued). "In this study, mutations in the genes ARID1A, APC, ERBB4, NCOR1, PDGFRA, ATM, and CDKN2A were either non-recurrent or of very low frequency, while none of the 14 sequenced EP tumours harboured mutations in the genes HRAS, EGFR, or RB1." (PMID 34045664, 2022). "RB1 is a well-established tumor suppressor, which not only governs progression across the G1 checkpoint, but also instigates DNA damage repair and GIN as novel functions to restrain tumor progression." (PMID 35406559, 2022). "Unlike DAM, which is usually a desmin-positive tumour with retained nuclear expression of RB1, CAF is desmin-negative, with the loss of nuclear RB1 immunoreactivity." (PMID 35204448, 2022). "Of note, we found a tumor without RB1 alteration, it belonged to subtype 2 and displayed a high level of MYCN amplification (141 copies)." (PMID 34552068, 2021). "Even though widespread apoptosis and reduced numbers of photoreceptor, ganglion, and bipolar cells were observed, retinoblastoma formation did not occur in organoids, suggesting that RB1 deletion alone is not sufficient for tumor development." (PMID 34638582, 2021). "Increased nuclear expression of RB1 [RB1(N)↑], CDH3(C)↑-STK17A(N)↑ and FLNA(C)↑-KRAS(C)↑were associated with survival, but not independent of tumor stage, where C and N denote cytoplasm and nucleus, respectively." (PMID 33936170, 2021). "Of the 398 IHC pairs, multivariate Cox regression analyses showed that CSNK1E↓-SHC1(N)↓, CSNK1E↓-RB1(N)↑, and BRCA1(N)↓-SHC1(N)↓ were significant predictors of the risk of death in this Taiwanese OSCC population, independent of tumor stage." (PMID 33936170, 2021). "Similar to RB1, genes that scored as hits both in the Drosophila eye screen and cancer cell line screens had least hazard than any other group of genes in patients with low expression levels of CDKN2A (p16Ink4a) in tumor samples." (PMID 33591981, 2021).